RN7SKP209 (RN7SK pseudogene 209)
Gene: Miscellaneous RNA gene on chromosome 6 (87,083,233 to 87,083,536, forward strand). Ensembl gene ENSG00000252697.
Homologues: Orthologues: chimpanzee 7SK (99% identical), mouse Gm55962 (41% identical). Paralogues in human: RN7SKP133 (57% identical), RN7SKP217 (57% identical), RN7SKP239 (57% identical), RN7SKP273 (57% identical), RN7SKP184 (57% identical), RN7SKP45 (57% identical), RN7SKP245 (56% identical), RN7SKP246 (56% identical), RN7SKP38 (56% identical), RN7SKP20 (56% identical), RN7SKP240 (56% identical), RN7SKP118 (56% identical), and 284 more.